NR2E1 (nuclear receptor subfamily 2 group E member 1)
Diseases named in the same sentence as NR2E1 in open-access papers:
NR2E1 is named in the same sentence as 43 diseases in open-access papers, as found by Europe PMC text mining. Sharing a sentence is not in itself a finding about the gene and the disease. The quoted sentences say what the papers report.
brain tumors (6 papers, 2015 to 2023). "Orphan nuclear receptor TLX (NR2E1) plays a critical role in the regulation of neural stem cells (NSC) as well as in the development of NSC-derived brain tumors." (PMID 30441799, 2018). "NR2E1‐positive glioma cells can initiate brain tumours and form spheres in suspension culture." (PMID 36321378, 2023). "NR2E1 may therefore be a valuable target for brain tumour therapy." (PMID 36321378, 2023). "Based on the yeast-two-hybrid screening of a human adult brain cDNA library, BCL11A was identified as a novel co-regulator of nuclear receptor subfamily 2 group E member 1 (TLX) and may associate with TLX-related functions, such as neural stem cells maintenance and brain tumors." (PMID 31654056, 2019). "Peptide LSD1‐197‐211 can repress BTICs by interfering the synergistic function of NR2E1 and LSD1 and may be a promising lead peptide for brain tumour therapy in future." (PMID 36321378, 2023). "Interestingly, NR2E1 was also moderately expressed at the later LNP stage, in correlation with its expression in mouse aNSC astrocytes as well as its role also in brain tumor initiation from NSCs45." (PMID 25799239, 2015).
glioblastoma (4 papers, 2012 to 2023). The most malignant astrocytic tumor (WHO grade IV). "High levels of the orphan nuclear receptor TLX (also known as NR2E1, Nuclear Receptor Subfamily 2 Group E Member 1) have been observed in glioblastoma and been shown to correlate with poor patient prognosis." (PMID 32073402, 2020). "Nuclear orphan receptor TLX (NR2E1) functions primarily as a transcriptional repressor and its pivotal role in brain development, glioblastoma, mental retardation and retinopathologies make it an attractive drug target." (PMID 22675500, 2012). "Gene expression analysis of glioma and glioblastoma cells revealed that Meis2 was one of the differentially expressed genes and it could be a prognostic biomarker for glioma and glioblastoma development, in addition to with other genes, including Meox2, Pitx2, Nr2e1, and Tfap2B." (PMID 33402862, 2020). "Since NR2E1 and LSD1 both play important roles in glioblastoma, we set out to investigate whether BTICs employ the same NR2E1‐LSD1 mechanism, as in NSCs, to regulate BTIC proliferation." (PMID 36321378, 2023).
prostate carcinoma (4 papers, 2016 to 2025). A carcinoma that arises from epithelial cells of the prostate gland. "Our previous study shows that the orphan nuclear receptor TLX (NR2E1), which is upregulated in prostate cancer, plays an oncogenic role in prostate carcinogenesis by suppressing oncogene-induced senescence." (PMID 29555975, 2018). "A recent study demonstrated that Nr2e1 also performs a positive role in prostate cancer growth regulation via its transcriptional coregulation of CDKN1A and SIRT1 genes." (PMID 26649147, 2016). "In addition, this interaction could be important during the development of prostate cancer where NR2E1 has been shown to have an oncogenic function." (PMID 27782803, 2016). "In agreement with our results, others reported that Nr2e1 plays important roles in the proliferation of both embryonic and adult NSC, retinal progenitor cells, and prostate cancer cells." (PMID 26649147, 2016).
breast carcinoma (3 papers, 2009 to 2020). "The association between FZD9 and NR2E1 immunoreactivity in different clinicopathological parameters in our patient cohort that consists of 80 breast cancer patients." (PMID 33304345, 2020). "Consistent with this targeted knock-down of NR2E1 inhibits the growth of different ER− breast cancer cell lines." (PMID 26894976, 2016). "In the case of NR2E1, this is line with the evidence present in the literature which indicates that targeting of the receptor is particularly promising in ER− mammary tumors." (PMID 26894976, 2016). "Two additional targets, the growth factor transcriptional repressor GFI1 gene (target number 8) and the nuclear receptor NR2E1 gene (target number 40), were inspected to evaluate the level of methylation in early-stage breast carcinomas." (PMID 19250546, 2009). "The results obtained from our IHC panel for both FZD9 and NR2E1 demonstrated the sensitivity of our shortlisted genes in discriminating between basal-like TNBC samples and other breast cancer molecular subtypes." (PMID 33304345, 2020). "As a proof of concept, we confirmed the clinical significance and prognostic value of two of the eight shortlisted genes (NR2E1, FZD9) belonging to this gene signature in our patient cohort consisting of 80 breast cancer patients." (PMID 33304345, 2020). "The group of NRs endowed with potential oncogenic properties in breast-cancer is smaller and consists of the Lipid-Sensors, NR1C2 and NR1I2, the Enigmatic-Orphans, NR1F3, NR3B1 and NR5A2, as well as the Orphan-Receptors, NR2E1, NR2E3 and NR6A1." (PMID 26894976, 2016). "Limited functional data on NR2E1 and NR2E3 are available and only few pertain to the breast-cancer realm." (PMID 26894976, 2016). "Low levels of NR2E1-mRNA and NR2E3-mRNA are detectable in mammary-glands and NR2E1 is further down-regulated in breast-cancers." (PMID 26894976, 2016). "Interestingly, NR2E1 was recently found to be upregulated in ERα-negative breast cancer and to play a role in breast cancer cell growth and invasion and was suggested as a possible candidate for therapeutic targeting." (PMID 33304345, 2020).
glioma (3 papers, 2018 to 2023). A benign or malignant brain and spinal cord tumor that arises from glial cells (astrocytes, oligodendrocytes, ependymal cells). "Western blot further confirms that neural stem cell marker NESTIN and NR2E1 were highly enriched in mouse and human BTICs as compared to the glioma cell lines U251, T98G and LN229." (PMID 36321378, 2023). "In humans, increased NR2E1 expression has been reported in glioma cell lines and glial tumours including astrocytomas." (PMID 28388012, 2018). "Recently, it has been demonstrated that Nr2e1 expression can activate postnatal NSCs in young mice, whereas overexpression in adult mice leads to a migration of NSCs from their natural niche, to the production of neurons and to the development of gliomas." (PMID 28388012, 2018). "This might be due to that these glioma cells do not rely on NR2E1 for cell growth." (PMID 36321378, 2023).
Retinal dystrophy (3 papers, 2014 to 2016). Retinal dystrophy is an abnormality of the retina associated with a hereditary process. "NR2E1-deficient mice can have hypoplasia of rhinencephalic and limbic structures—including the olfactory, infra-rhinal and entorhinal cortex, amygdala and dentate gyrus—enlarged ventricles, hydrocephalus, retinal dystrophy, blindness and aggression." (PMID 24466353, 2014). "Nr2e1-null mice exhibit reduced cortical and limbic structures and pronounced retinal dystrophy." (PMID 27782803, 2016). "Moreover, we have shown that prevention of retinal dystrophy is not regulated cell-autonomously by Nr2e1." (PMID 26092486, 2015). "However, Nr2e1 does not have a cell-autonomous role in preventing retinal dystrophy." (PMID 26092486, 2015).
bipolar disorder (2 papers, 2009 to 2012). A disorder of the brain that causes unusual shifts in mood, energy, activity levels and the ability to carry out day-to-day tasks. "The role of NR2E1 in human disease is starting to be recognized as the genomic variation has been associated with bipolar disorder, and overexpression in gliomas correlates with decreased survival of patients with brain tumors." (PMID 23213277, 2012). "Another nuclear receptor, NR2E1, has been reported to be associated with bipolar disorder in a case-control study: there has been brief mention that NR2E1 and NR1D1 may interact in the development of photoreceptors." (PMID 19166596, 2009).
microcephaly (2 papers, 2007). A congenital or acquired developmental disorder in which the circumference of the head is smaller than normal for the person's age and sex. "In this regard, it is conceivable that one or more of the human-specific NR2E1 sites identified in the present study may have been fixed by positive selection in a manner similar to that proposed for ASPM, which is mutated in some patients with microcephaly." (PMID 17054721, 2007).
microphthalmia (2 papers, 2007 to 2012). Congenital or developmental anomaly in which the eyeballs are abnormally small. "To test this hypothesis, we screened NR2E1 for candidate mutations in patients with aniridia and other congenital ocular malformations (anterior segment dysgenesis, congenital optic nerve malformation, and microphthalmia)." (PMID 23213277, 2012).
Obesity (2 papers, 2020 to 2024). Accumulation of substantial excess body fat. "Another study showed that Nr2e1 could function as a target for improving insulin sensitivity and inflammation in obesity and associated problems." (PMID 39408930, 2024).
schizophrenia (2 papers, 2015 to 2022). A major psychotic disorder characterized by abnormalities in the perception or expression of reality. "Human NR2E1 has been associated with bipolar disease, schizophrenia, and psychopathy, diseases known for their association with abnormal aggression, but the evidence for NR2E1 directly affecting aggression in humans is certainly limited." (PMID 26312756, 2015).
aniridia (1 paper, 2012). Aniridia is a congenital ocular malformation characterized by the complete or partial absence of the iris. "The NR2E1 coding region, 5′ and 3′ untranslated regions (UTRs), exon flanking regions including consensus splice sites, and six evolutionarily conserved non-coding candidate regulatory regions were analyzed by sequencing 58 probands with aniridia of whom 42 were negative for PAX6 mutations." (PMID 23213277, 2012).
autism spectrum disorder (1 paper, 2017). A spectrum of developmental disorders that includes autism, and Asperger syndrome. "Interestingly, several genes (Adcyap1, Cntnap2, Grid1, Nrxn1, Nrxn3, Ucn, Tbx1, and Nr2e1), that are associated with disorders, stress response, social behaviors or autism spectrum disorders, are up-regulated specifically in the hippocampus of Del/+ mice." (PMID 28704368, 2017).
behavior disorders (1 paper, 2007). "The knowledge of the genetic architecture of NR2E1 generated in this study in ethnically diverse humans and non-human primates provides additional tools for future disease-mapping studies of brain–behavior disorders." (PMID 17054721, 2007).
Cognitive impairment (1 paper, 2007). Abnormal cognition is characterized by deficits in thinking, reasoning, or remembering. "NR2E1 is also a strong functional candidate, given that mice deleted for Nr2e1 present with a complex MMEP-related phenotype that includes forebrain hypoplasia, eye abnormalities, and cognitive impairment, which is consistent with the brain and eye expression pattern of this gene." (PMID 17655765, 2007).
diabetes (1 paper, 2016). "Together, this study indicated a potential protective effect of Nr2e1 on beta cells, which may serve as a target for the development of novel therapies for diabetes." (PMID 26649147, 2016).
hepatocellular carcinoma (1 paper, 2025). A malignant tumor that arises from hepatocytes. "On the other hand, the NR2E1 gene is silenced by hypermethylation mechanisms in hepatocellular carcinomas and lung carcinomas." (PMID 39858027, 2025).
Hyperglycemia (1 paper, 2016). An increased concentration of glucose in the blood. "Whether or not Nr2e1 is involved in the etiology of beta cell failure and hyperglycemia in T2D rodent models will require further investigations." (PMID 26649147, 2016).
melanoma (1 paper, 2012). A malignant, usually aggressive tumor composed of atypical, neoplastic melanocytes. "Furthermore, a database search for NR2E1 coding variants revealed the Arg274Gln variant (dbSNP, rs148906882), found in a melanoma sample and thus of potential biologic significance." (PMID 23213277, 2012).
neuroblastoma (1 paper, 2020). Neuroblastoma (NB) is the most common solid, extracranial childhood tumor. "Interestingly, the mammalian Tll homolog TLX/NR2E1 acts as self-renewal factor in neural stem cells and neuroblastoma tumor spheres, and elevated expression of TLX/NR2E1 is correlated with an unfavorable prognosis in neuroblastoma patients." (PMID 32917927, 2020).
retinoblastoma (1 paper, 2023). A malignant tumor that originates in the nuclear layer of the retina. "Through coordinated repression of Pten, NR2E1 and LSD1 contribute to the proliferation of NSCs and retinoblastoma cells." (PMID 36321378, 2023).
Stroke (1 paper, 2024). Sudden impairment of blood flow to a part of the brain due to occlusion or rupture of an artery to the brain. "Here, we show that stroke-induced neurogenesis is dramatically increased with the additional expression of two copies of the nuclear receptor-coding gene tailless (Tlx, also known as Nr2e1), which has been shown to be a master regulator of subventricular zone (SVZ) neural stem cells (NSCs)." (PMID 39596503, 2024).
tumor (7 papers, 2010 to 2025). "This ecDNA harbors the TF NR2E1 (TLX), which has been implicated in tumor immune suppression and immune cell infiltration." (PMID 41360770, 2025). "In this study, we identified NR2E1 to have significantly higher gene body methylation in cortical relative to midline and infratentorial tumours." (PMID 28388012, 2018). "who also identified hypermethylation in the gene body of NR2E1 in supratentorial tumours in comparison with infratentorial tumours." (PMID 28388012, 2018). "Depletion of Nr2e1 in mouse primary tumours significantly extended animal survival time." (PMID 36321378, 2023). "Specific hypermethylation of NEUROG1 and NR2E1 was identified as a feature of cortical tumours." (PMID 28388012, 2018). "NR2E1 and its interacting protein‐LSD1 in BTICs were studied by gene interference combined with cell growth, tumour sphere formation, co‐immunoprecipitation and chromatin immunoprecipitation assays." (PMID 36321378, 2023). "NR2E1 and NEUROG1 had significantly higher levels of methylation in cortical tumours relative to infratentorial and midline tumours (P ≤ 0.05)." (PMID 28388012, 2018). "Infratentorial tumours also had significantly lower levels of methylation in NR2E1 and NEUROG1 when compared to midline tumours (P ≤ 0.01)." (PMID 28388012, 2018). "Despite the previous work showing differential expression depending on tumour location, in the current study we showed variable expression of the NR2E1 protein across all tumours irrespective of location, as well as within tumours." (PMID 28388012, 2018).
cancer (4 papers, 2015 to 2025). A tumor composed of atypical neoplastic, often pleomorphic cells that invade other tissues. "Surprisingly, NR2E1 was the only NR to display similar expression levels (high expression) in association with overall survival in all cancer types (BRCA, CESC, OV, and UCEC) within a pan-cancer organ system (gynecologic pan-cancers)." (PMID 32024906, 2020). "Gene clusters upregulated at the NE towards E-RG stage were enriched for nervous system morphogenesis (P=1.2E−7) and cancer associated factors (P=6.9E−8) and included genes such as NR2E1 and LGR5." (PMID 25799239, 2015). "For example, the ability of miR‐9 to inhibit cell proliferation has been linked to downregulation of MTHFD2 expression in cancer cells or TLX/NR2E1 in neural stem cells." (PMID 26416703, 2015). "NR2E1 was the only NR to demonstrate an association between similar expression patterns and shorter overall survival rates in all cancer types within a ‘Pan-Cancer’ organ system (high NR2E1 expression in BRCA, CESC, OV, and UCEC among gynecologic pan-cancers)." (PMID 32024906, 2020).
brain diseases (1 paper, 2024). "Among the genes annotated to SOX2-bound elements, numerous have been associated with astrogliosis and reactive astrocyte proliferation after TBI or other brain diseases, such as Nr2e1, Mmd2, Wnt7a, and Akt2." (PMID 38672150, 2024).
eye disorder (1 paper, 2012). A non-neoplastic or neoplastic disorder that affects the eye. "Based on these data, we undertook the first screening for NR2E1 mutations focused on human eye disorders." (PMID 23213277, 2012). "Thus, due to the important role that NR2E1 plays during eye development, we hypothesize that NR2E1 may be involved in human eye disorders impacting a wide range of eye structures whose development depend on NR2E1 genetic interactors such as PAX2 and PAX6." (PMID 23213277, 2012).
metabolism disorders (1 paper, 2024). "One study showed that increased Nr2e1 levels may be linked to inflammation and lipid and glucose metabolism disorders in diabetic individuals." (PMID 39408930, 2024).
NR2E1 also shares sentences with these, for which no sentence is quoted: astrocytomas (1 paper); bladder cancer (1); Blindness (1); breast tumors (1); cervical cancer (1); cutaneous melanoma (1); epilepsy (1); Hydrocephalus (1); leiomyosarcoma (1); lung carcinoma (1); non-alcoholic fatty liver disease (1); optic nerve hypoplasia (1); prostate (1); renal carcinoma (1); retinitis pigmentosa (1); Sandhoff disease (1).